BRAF (B-Raf proto-oncogene, serine/threonine kinase)
Diseases named in the same sentence as BRAF in open-access papers (continued):
Sharing a sentence is not in itself a finding about the gene and the disease.
melanoma (continued). "Inhibition of the BRAF V600E oncoprotein by small-molecule drugs, such as vemurafenib (PLX4032) or PLX4720, results in marked antitumor activity in human melanoma cells carrying the BRAF V600E mutation." (PMID 29033690, 2017). "Between 40–50% of human melanomas harbour activating mutations in BRAF, while approximately 15–20% of melanomas possess mutations in the NRAS gene." (PMID 28380427, 2017). "Due to the disparity between common human melanomas and Kdm2aa-deficient tumours this melanoma model is different from classic BRAF mutation model systems." (PMID 28806732, 2017). "A recent study based on 213 human melanoma samples identified three frequently mutated genes: BRAF, NRAS and NF1, with frequencies of 38.5, 28.6 and 12.2%, respectively." (PMID 28637487, 2017). "Specific BRAF mutations when pretreated with Dabrafenib have been associated with reduced response to PD-1/PD-L1 inhibition in melanoma." (PMID 28331612, 2017). "BRAF inhibitors (BRAFi) are active only in melanoma cells bearing V600 BRAF mutations, where this kinase is present as constitutively active monomers." (PMID 28118616, 2017). "We show that inhibition of PDKs by AZD7545 leads to growth suppression of BRAF-mutated and -inhibitor resistant melanoma cells." (PMID 28595656, 2017). "Our current panel incorporates KRAS, NRAS, EGFR, and BRAF for combined screening of common mutations in colorectal cancer, lung cancer and melanoma, known as the REB array." (PMID 28228113, 2017). "The discovery of BRAF mutations in melanoma and the development of specific BRAF inhibitors has led to significant advances in treatment of metastatic melanoma, which has now been further improved by the use of new immunologic therapy." (PMID 28039443, 2017). "Excitingly, these results were observed even in the melanomas that have relapsed from molecular-targeted or immune-therapies and also those with varying genetic backgrounds (wild type or mutated for BRAF, NRAS, or NF1)." (PMID 27086916, 2017). "In an attempt to identify therapeutic options for the BRAF wild‐type melanomas, there are now several clinical trials using mutational profiles for patient stratification (ClinicalTrials.gov identifier: NCT02645149, NCT02094872)." (PMID 28267273, 2017). "In the last ten years, the discovery of BRAF mutations in melanoma created the first opportunity to develop oncogene-directed therapy, which had produced major clinical responses and significantly improved survivals." (PMID 29113311, 2017). "The missense mutation, V600E, results in a substitution from valine to glutamic acid at the 600th amino acid position and represents the majority (80%) of all BRAF activating mutations in melanoma." (PMID 29276510, 2017). "Vemurafenib, a BRAF inhibitor, has been shown to improve outcomes in the majority of melanoma patients harbouring BRAF V600E mutation, with a median overall survival (OS) of approximately 16 months." (PMID 29202777, 2017). "Between 11/2012 and 12/2015, 23 patients with stage IIIC BRAF V600E/K mutated melanoma provided written informed consent and enrolled in the study." (PMID 29285228, 2017). "The 98 melanoma samples were screened for BRAF mutations by ARMS/Scorpion real-time PCR and hybridization with biochips." (PMID 28881731, 2017). "We postulate that the LKB1 knockdown synergism with BRAF mutation promote melanoma cells invasion and migration in vitro." (PMID 29371951, 2017). "The genetic mutations such as over-activation of BRAF and Ras, which are found in respectively around 50% and 20% of metastatic melanomas, favor melanoma cell over-proliferation and tumor progression." (PMID 28567163, 2017).
melanoma (continued). "Previous study found that mutations in BRAF can be found in 8% of human cancers, including 59% of melanomas, 30–70% of thyroid cancers, 30% of cancers of the ovary of low grade and 10% of colorectal cancers." (PMID 29137342, 2017). "We confirmed the positive BRAF mutational status obtained with our previous results, in primary melanoma at high rates (30, 47 and 41 % of mutated alleles, respectively) and lack of BRAF mutation in the metastatic samples." (PMID 28039443, 2017). "Actually, the reasonable explanation for these differences was there existing molecule interaction between different signal pathways during the BRAF mutated melanoma progression." (PMID 29371951, 2017). "As such, routine genetic testing of melanoma patients for TERT promoter mutations in addition to mutant BRAF and NRAS would be clinically beneficial." (PMID 29108273, 2017). "BRAF (V600E) mutation is also commonly detected in other tumors such as melanoma and colorectal cancer." (PMID 27880942, 2017). "Over the last decade, BRAF-targeted therapies and drug development have focused specifically on inhibition of V600E mutated BRAF, mainly due to the high proportion of V600E mutations in melanoma." (PMID 28947956, 2017). "proved that FBXO4 deficiency induces melanoma in BRAF‐activated mice, with the expression of cyclin D accumulated in the nucleus of melanoma cells in the presence of FBXO4 inactivation." (PMID 28544818, 2017). "The higher proportion of non-V600E genotypes in BRAF-mutated melanomas was observed in older patients (P = 0.05)." (PMID 28881731, 2017). "Although targeted therapy has been tested for NRAS mutated melanoma, response rates still appear much weaker, than in BRAF mutated melanoma." (PMID 28522871, 2017). "Clinical resistance to BRAF inhibitors has been found to be associated with increased PD-L1 expression on melanoma cells." (PMID 28848761, 2017). "Several reports based on in vitro and in vivo models of melanoma and clinical studies of melanoma patients have demonstrated a link between activating mutations at codon V600 of BRAF (most commonly BRAFV600E) and aerobic glycolysis." (PMID 29137417, 2017). "The BRAF‐mutated COLO205 and OXCO‐1 CRC cells and the COLO741 melanoma cells display impaired proliferation when treated with BRAF inhibitor vemurafenib." (PMID 28182330, 2017). "TAK-632 was shown to induce minimal paradoxical activation and potent antiproliferative effects in preclinical NRAS- and BRAF-mutated melanoma models." (PMID 28002790, 2017). "One of the MPNST cell lines, STS26T, had an oncogenic V600E mutation in BRAF, which is a known marker for benefit of BRAF inhibition in melanoma." (PMID 28556483, 2017). "We thank Meenhard Herlyn (Wistar Institute, Philadelphia, Pennsylvania), Kimberly Dahlman, and Ann Richmond for kindly providing BRAF mutated melanoma cell lines." (PMID 28205616, 2017). "The discovery of mutations in BRAF in melanoma lead to the development of vemurafenib, an orally available and well-tolerated selective inhibitor of BRAF V600E, for the treatment of patients with advanced disease." (PMID 29291012, 2017). "Among the mutations involved in melanoma pathogenesis, those repeatedly identified from BRAF and NRAS oncogenes have been investigated." (PMID 29229974, 2017). "Since the discovery of BRAF mutations in melanoma patients (50-60%), numerous small molecule inhibitors have been tested on melanoma." (PMID 29299138, 2017). "For melanoma cell lines, the preeminent factors are the presence of the most significantly mutated genes (BRAF, NRAS, NF1, or triple wild type) and proliferative or invasive behavior (MITF/AXL expression ratio)." (PMID 29383127, 2017). "Altogether, putatively druggable variants were found in ≈ 25% (23 of 93) of BRAF-wt/RAS-wt melanoma patients, with 6 patients having two possible drug-gene combinations." (PMID 28545463, 2017).
melanoma (continued). "According to trial CA209037, the objective response rate (ORR) in the PDL-1 positive was 43.6%, 20.3% in PDL-1 negative patients, 23.1% in those patients who have BRAF V600 mutation-positive melanoma, and 34% in BRAF wild-type melanoma." (PMID 28878676, 2017). "Based on the PLX4720-treated DIP rates, BRAF-mutated melanoma cell lines fall along a response spectrum or continuum, from highly sensitive (e.g., WM164) to largely insensitive (A2058)." (PMID 28205616, 2017). "Enoxacin strongly inhibited the growth of melanoma cells carrying the most common BRAF kinase oncogenic mutation V600E (Mel-Ho, A375), as well as the proliferation of cells with activating mutations in the NRAS oncogene (Mel-Juso)." (PMID 28973015, 2017). "This study highlights the potential of RCM as a supplementary tool in the screening of BRAF-mutated melanomas." (PMID 28662062, 2017). "The detection of BRAF mutations in isolated CTCs from BRAF-mutated melanoma patients has been performed after an obligatory step of whole genome amplification (WGA)." (PMID 28484715, 2017). "Melanoma frequently originates due to mutation in the BRAF and NRAS genes (43% and 30% of cases, respectively)." (PMID 28718799, 2017). "Mutations in the Ser/Thr-kinase BRAF have been found in 10% of all human cancers with the highest prevalence observed in melanoma patients (>50%), making BRAF one of the most mutated cancer-associated genes." (PMID 28595656, 2017). "Somatic mutations in many cancers including colon carcinoma, melanoma, or pancreatic cancer are often found in BRAF, KRAS, or NRAS." (PMID 28537899, 2017). "Despite initially promising clinical results in V600E BRAF-mutated melanoma, Vemurafenib and Dabrafenib monotherapies ultimately end with drug resistance and relapse of the cancer." (PMID 28947956, 2017). "The most commonly activated pathway in melanoma is the mitogen‐activated protein kinase (MAPK) pathway, often constitutively activated through mutations in the V600 codon of BRAF (in 35–50% of melanomas) and the Q61 codon of NRAS (10–25%)." (PMID 28267273, 2017). "Our findings provided evidence for the feasibility of combination therapy with EZH2 and BRAF inhibitors in melanoma with concurrent BRAF V600E mutation and EZH2 gain." (PMID 29202777, 2017). "Increased PAK1 expression is also present in BRAF wild type melanoma compared with BRAF mutated disease." (PMID 27845911, 2017). "Following these studies, another group showed that SGK3 together with PDK1 are implicated in melanomas harbouring BRAF mutations and wild type PTEN, which in fact account for more than half the cases of melanomas occurrence." (PMID 29064423, 2017). "The study on efficient detection of genomic drivers in malignant melanoma identified co-occurrence of a mutational and copy number hotspot on chromosome 7 including the known BRAF locus." (PMID 28265786, 2017). "The B-raf gene is mutated in up to 66% of human malignant melanomas, and its protein product, BRAF kinase, is a key part of RAS-RAF-MEK-ERK (MAPK) pathway of cancer cell proliferation." (PMID 28724377, 2017). "One previous study evaluated six BRAF V600E mutated primary melanomas and 2 metastasis with RCM and found them to reveal pleomorphic pagetoid cells, disarrangement of the dermal-epidermal junction, discohesive junctional nests and bright particles at the DEJ." (PMID 28662062, 2017). "BRAF amplifications have been described in various frequencies in melanomas (5.6-66%) and seemed to be associated with decreased progression free survival (PFS), independent of the underlying BRAF mutation." (PMID 29312620, 2017). "While Richard Marais put forward a different viewpoint on treatment of BRAF mutated melanoma with AMPK activator metformin." (PMID 29371951, 2017). "Scientists know that around 60% of the melanoma cells are directly related to the BRAF gene mutation." (PMID 28303522, 2017).
melanoma (continued). "A 71-year-old female with BRAF mutation–positive melanoma presented with metastases to the lungs, spleen, abdominal lymph nodes, sternum, right lateral sixth rib, and right ilium subsequent to disease progression on vemurafenib (Zelboraf)." (PMID 29900017, 2017). "BRAF mutations are found in 40–60% of melanomas, with a valine to glutamic acid substitution at residue 600 (V600E) as the most common variant (75–80%), followed by substitution to lysine (V600K, 17–22%) and arginine (V600R, 3–4%)." (PMID 29179523, 2017). "Activating mutations in the BRAF oncogene occur in approximately 7% of human malignancies, including 50–60% of melanomas and 5–8% of colorectal cancers (CRCs)." (PMID 27974353, 2017). "A recently published study analysed the transcriptome profile of BRAF-mutated melanoma tumors derived from 21 patients either at the beginning of their treatment with BRAF inhibitors or at the time of disease progression." (PMID 29299138, 2017). "Meta-Analysis of randomized clinical trials show that compared with other treatments of advanced BRAF-mutated melanoma, combined BRAF/MEK and PD-1 inhibitions significantly improved overall survival time." (PMID 28724377, 2017). "Treatment of patients with metastatic BRAF V600E/K-mutated melanoma with the FDA approved RAF inhibitors, vemurafenib and dabrafenib, leads to rapid tumor shrinkage in most patients." (PMID 29285228, 2017). "We report here that treatment with BRAF or MEK inhibitors upregulates CD47 in melanoma cells in vitro and in vivo, and that melanoma cells resistant to BRAF inhibitors are more susceptible to macrophage phagocytosis upon CD47 blockade." (PMID 29050218, 2017). "Decreased expression of miR-193 is usually associated with tumorigenesis, such as oral squamous cell carcinoma, acute myeloid leukemia, lung cancer, BRAF-mutated melanoma, etc." (PMID 29245933, 2017). "This is consistent with our findings of stimulating effects of Metformin on VEGF and HIF-1α in WM35 melanoma, since this cell type exhibits the BRAF-V600E-mutation." (PMID 28278159, 2017). "In our primary melanoma series, BRAF mutations were the most prevalent (50%) followed by TERT promoter mutations (33%)." (PMID 28356599, 2017). "The benefit of combined therapy with Dabrafenib and Trametinib has been demonstrated in V600 BRAF mutated melanoma, NSCLC and colorectal cancer (CRC)." (PMID 28947956, 2017). "The B-raf gene is mutated in up to 66% of human malignant melanomas, and its protein product, BRAF kinase, is a key part of the RAS-RAF-MEK-ERK (MAPK) pathway of cancer cell proliferation." (PMID 28724377, 2017). "Combination therapy with selumetinib plus dacarbazine has also been compared with placebo plus dacarbazine as first-line treatment in patients with BRAF mutated melanoma in a phase II study." (PMID 28954413, 2017). "Predictably, melanomas expressing BRAF splice variants display MAPK re-activation in the presence of BRAF inhibitors, and retain sensitivity to the inhibition of the downstream kinases MEK and ERK." (PMID 28503307, 2017). "Two BRAF inhibitors (vemurafenib and dabrafenib) and one MEK inhibitor (trametinib) are recently approved for the treatment of metastatic BRAF V600E mutated melanoma." (PMID 29312620, 2017). "In hindsight, the simultaneous finding of a BRAF mutation, combined with the localization and morphology of the tumor, should have aroused our suspicion of an aberrant malignant melanoma." (PMID 28343447, 2017). "Locoregional treatment with surgery, radiotherapy, radiosurgery, and newer drug classes such as checkpoint inhibitors and targeted agents against BRAF-mutation melanoma have shown limited effectiveness against MBM32." (PMID 29129918, 2017).
melanoma (continued). "The presence of these mutations has led to the development and approval of two BRAF inhibitors (BRAFi) for melanoma treatment, namely, vemurafenib (Genentech/Plexxikon) and dabrafenib (GlaxoSmithKline) as well as, a MEK inhibitor trametinib (GSK)." (PMID 29276510, 2017). "In more than 90% of the BRAF-mutant melanoma cases, the activating mutation is V600E in the BRAF kinase." (PMID 28596940, 2017). "For example, study of the V600E mutation in BRAF in melanoma led to the development of B-Raf inhibitors that years later, have shown potential efficacy in craniopharyngioma." (PMID 28555425, 2017). "BRAF inhibitor and dual BRAF/MEK inhibitors have been approved for the treatment of BRAF-mutated melanoma." (PMID 29137342, 2017). "A predictive marker for BRAF inhibitors in melanoma is the BRAF V600E mutation, where positive tumors have a high response rate with increased progression-free survival for patients and when combined with a MEK inhibitor there is increased overall survival." (PMID 28343447, 2017). "Melanomas harboring BRAF mutation (V600E) are known to recur frequently following treatment with BRAF inhibitors (BRAFi) despite a high initial response rate." (PMID 29094484, 2017). "In a murine model of BRAF-mutated melanoma, host NK cells and perforin were required for the effect of a BRAF inhibitor and correlated with the reduction of tumor growth, and an increased NK and T cell infiltration of the tumors." (PMID 28659921, 2017). "The use of these in vitro models has propelled our understanding of molecular cancer biology and led to numerous landmark discoveries, such as the prevalence of BRAF V600E mutations in melanoma." (PMID 28060736, 2017). "Mutations of BRAF are critical drivers of the melanoma proliferation in approximately 50-60% of cutaneous melanomas whereas those of NRAS recur in 10-20% of patients and are a negative prognostic factor." (PMID 29285320, 2017). "In the case of genomic MAPK activation (subtype I), the BRAF status as well as signature UV mutations provide insight into the molecular origin of melanoma." (PMID 28265786, 2017). "Confirming the screen results, varying concentrations of ganetespib increased the sensitivity of 2549 and 2338, and additional human melanoma cell lines 2400 and 2559 (BRAF V600E mutated), 2812 (wild type for BRAF, NRAS and cKIT) to T-cell-mediated killing." (PMID 28878208, 2017). "Approximately 50% of melanomas carry mutations in the gene encoding BRAF, part of the MAPK pathway involved in regulating cell growth and proliferation." (PMID 29100459, 2017). "For example, melanomas with BRAF mutations respond well to B-Raf inhibitors, but the same is not true in colorectal cancer." (PMID 28725482, 2017). "Consistent with this, it has been reported that approximately 50% of melanomas carry an active mutation in BRAF, which renders the MAPK signaling pathway constitutively active." (PMID 29187213, 2017). "As an example of this nuance, in melanoma the hot-spot V600 and K601 BRAF mutations are significantly exclusive from NRAS hot-spot mutations." (PMID 29118384, 2017). "From a clinical viewpoint, MAPK pathway inhibitors induce a relatively short-lived tumor response in most patients with BRAF-mutated melanoma." (PMID 29100459, 2017). "The findings of the present study reveals that BRAF V600E mutated melanomas tend to have epidermal and DEJ nests, are of the superficial spreading type, occur at a younger age, and are located on intermittently sun exposed areas." (PMID 28662062, 2017). "AXL also regulates melanoma growth and migration and has been implicated in resistance to BRAF inhibition." (PMID 28103611, 2017). "The average thickness of the melanoma lesions in 59 patients with the BRAF V600E mutation was 4.8 mm, consistent with the observation that thickness in Chinese patients is thicker than that in Caucasians." (PMID 29202777, 2017).